SIRT1 (sirtuin 1)
Diseases named in the same sentence as SIRT1 in open-access papers (continued):
Sharing a sentence is not in itself a finding about the gene and the disease.
ovarian carcinoma (continued). "However, SIRT1 is frequently overexpressed in ovarian cancer tissues compared to normal ovarian epithelium." (PMID 41300302, 2025). "Furthermore, SIRT1 is involved in regulating chemoresistance, a major challenge in ovarian cancer treatment." (PMID 41300302, 2025). "Additionally, HOTAIR acts as a sponge for MIR138-5p, preventing its interaction with EZH2 (enhancer of zeste 2 polycomb repressive complex 2 subunit) and SIRT1 (sirtuin 1), thus enhancing the resistance of ovarian cancer cells to cisplatin-based chemotherapy." (PMID 39684286, 2024). "In ovarian cancer cells, cytoplasmic SIRT1 inhibits cell migration and invasion by impeding EMT." (PMID 37894746, 2023). "In ovarian cancer cells, SIRT1 can promote cell migration by deacetylating cortactin." (PMID 37894746, 2023). "Therefore, it is of value to study the mechanism of action of SIRT1 in ovarian cancer and other related diseases, and to target SIRT1 in the development of appropriate drugs, such as specific inhibitors." (PMID 36975503, 2023). "The SIRT1/HMGB1 axis may therefore be a key therapeutic target for inhibiting ovarian cancer migration, thus attenuating the progression of this disease." (PMID 36081910, 2022). "SIRT1 significantly stimulated ROS formation in ovarian cancer cells." (PMID 36143462, 2022). "This study aimed to analyze RXRα and Sirt1 as potential therapeutic targets in ovarian cancer." (PMID 34870752, 2022). "Some authors indicated that SIRT1 is overexpressed in women with ovarian carcinoma." (PMID 33435147, 2021). "Moreover, Sirt1 is found to be coordinately overexpressed with KRAS and likely participates in the pathogenesis of endometriosis-associated ovarian cancer." (PMID 34955846, 2021). "As a final conclusion, the authors summarized that HIF1α and SIRT1 might serve as potential therapeutic targets for ovarian cancer, establishing an interesting connection between different pathways of observed disturbances and cancer pathogenesis." (PMID 33435147, 2021). "SIRT1 was overexpressed in ovarian cancer cell exposure to hypoxia condition, and the NF-κB signaling pathway was involved in hypoxia-induced SIRT1 up-regulation—HIF-1α promoted CSCs-like features by increasing SIRT1 expression via NF-κB signaling pathway activation." (PMID 33435147, 2021). "In ovarian cancer, SIRT1 overexpression was correlated with improved overall survival." (PMID 32388637, 2020). "Therefore, our data suggest that MHY2245 inhibited ovarian cancer cell proliferation and induced autophagy by inhibiting the SIRT1/Akt/mTOR pathway." (PMID 32398958, 2020). "Herein, we evaluated if and how SRT2183, a sirtuin-1 activator, impairs the ovarian cancer cells." (PMID 33223507, 2020). "In contrast, Sirt1 levels were decreased in various cancer tissues including bladder, prostate and ovarian cancers, implying that Sirt1 might be a tumor suppressor." (PMID 32698385, 2020). "In addition, SIRT1 levels decrease in some human cancers including glioma, bladder, and ovarian cancer." (PMID 31956359, 2020). "As a result, controlling the expression of SIRT1 might be an alternative approach to manage the PI3K/Akt/mTOR pathway in ovarian cancer cells." (PMID 32398958, 2020). "Altogether, our findings may highlight a novel role of cytoplasmic SIRT1 in ovarian carcinoma, providing new possible insights for studies investigating the role of SIRT1 in tumor progression." (PMID 31317367, 2019). "In addition, in ovarian carcinoma, the roles of SIRT1 in tumor progression remain highly controversial." (PMID 31317367, 2019). "In addition, a variety of human cancers including glioma, bladder, prostate, and ovarian cancer display decreased levels of SIRT1." (PMID 30761005, 2019). "Overall, the results of the comparative analyses of the proteome and lysine acetylome indicate that the wild-type SIRT1 protein and cytoplasm-localized SIRT1 protein differentially influence the epithelial phenotype and cell adhesion in ovarian carcinoma cells." (PMID 31317367, 2019).
ovarian carcinoma (continued). "Altogether, our findings may highlight a novel function of cytoplasmic SIRT1 in ovarian carcinoma, providing new possible insight for studies investigating the role of SIRT1 in tumor progression." (PMID 31317367, 2019). "Here, we report that cytoplasmic SIRT1 acts as a tumor suppressor in ovarian carcinoma." (PMID 31317367, 2019). "Additionally, Sirt1 has been identified as a target of microRNA-142 (miR-142), increasing its expressions in the ascites and sera of ovarian cancer patients." (PMID 31038546, 2019). "In summary, presented data suggest that selective targeting of ERβ with an agonist potentiate chemotherapy efficacy for the treatment of ovarian cancer and that downregulation or inhibition of SIRT1 may further enhance its therapeutic effect." (PMID 29422491, 2018). "Presented data suggest that selective targeting of ERβ with an agonist potentiate chemotherapy efficacy for the treatment of ovarian cancer and that downregulation or inhibition of SIRT1 may further enhance its therapeutic effect." (PMID 29422491, 2018). "SIRT1 modulates cisplatin sensitivity in ovarian cancer via BRCA1-SIRT1-EGFR signaling." (PMID 30064416, 2018). "SIRT1 over-expression is pivotal in malignant ovarian tumor chemo-resistance, and may serve as a predictive indicator of poor clinical outcome." (PMID 30064416, 2018). "Our data suggested that HIF-1α and SIRT1 could be predictors for chemoresistance and prognosis of ovarian cancer and they will be the targets for the development of new therapies for ovarian cancer." (PMID 28878214, 2017). "Our results hinted that HIF1α and SIRT1 might serve as potential therapeutic targets for ovarian cancer." (PMID 28878214, 2017). "The results of this study indicated that in ovarian cancer HIF1α and SIRT1 might serve as potential therapeutic targets." (PMID 28878214, 2017). "SIRT1 level is actually lower in hepatic cell carcinoma, bladder carcinoma and ovarian cancer indicating that SIRT1 may act as a tumor suppressor." (PMID 28903430, 2017). "As β-catenin is constitutively activated in many human tumors including ovarian cancer and melanoma, SIRT1 may inhibit the growth of these tumors by deacetylating and inactivating β-catenin." (PMID 26992208, 2016). "Interestingly, SIRT1 is a direct target of miRNA-142-3p in ovarian cancer." (PMID 38663003, 2024). "More importantly, it was found that gerberoside decreased SIRT1 expression, thereby attenuating the nuclear accumulation of β-catenin and subsequently inhibiting Wnt/β-catenin signaling, thus sensitizing cisplatin-resistant ovarian cancer cells to chemotherapy." (PMID 36975503, 2023). "Due to the high abundance of SIRT1 in ovarian tissues, especially in granulosa cells, in addition to its involvement in the regulation of ovarian-related diseases such as PCOS, POI, POR, etc., some studies have implicated SIRT1 as a key transcription factor in the regulation of ovarian cancer." (PMID 36975503, 2023). "Therefore, restoration of SIRT1 expression through targeting the sumoylation pathway could be a strategy to combat metastasis in ovarian cancer." (PMID 35887358, 2022). "Moreover, we demonstrated that miR-138-5p could directly regulate the expression of EZH2 and SIRT1, which have been proven to be involved in regulation of cisplatin resistance of ovarian cancer." (PMID 32349783, 2020). "Moreover, SIRT1 may play a role in the acquisition of aggressiveness and chemoresistance in ovarian cancer and have potential as a therapeutic target for ovarian cancer." (PMID 31956359, 2020). "Also in regard to other gynecologic tumors, such as ovarian cancer, the role of SIRT1 expression is inconsistent: regarding the most common ovarian cancer types (serous, mucinous, endometrioid, clear-cell), an increased SIRT1 expression is significantly correlated to shorter survival rates." (PMID 32388637, 2020).
ovarian carcinoma (continued). "Therefore, poor prognosis of DBC1-expressing ovarian carcinoma might be related to its inhibitory role for SIRT1." (PMID 25823848, 2015). "In ovarian cancer, NF-κB, mediated by HIF-1α, induces cancer stem cell characteristics by increasing sirtuin 1 (SIRT1)." (PMID 40420174, 2025). "This shift from previous research suggests a tissue-specific and context-dependent immunosuppressive role of SIRT1 in CRC and ovarian cancer, but an immune-enhancing role in melanoma." (PMID 41425553, 2025). "Future studies should investigate the subtype-specific roles of SIRT1 in redox adaptation and therapy resistance, particularly in HGSC, which is the most lethal form of ovarian cancer." (PMID 41008982, 2025). "Deacetylation and inhibition the cytosolic release of HMGB1 by sirtuin 1 (SIRT1) inhibits migration and angiogenesis in ovarian cancer cells." (PMID 38725632, 2024). "SIRT1 and KLF4 inhibit the migration and invasion of ovarian cancer cells by activating the transcription of CLDN5." (PMID 37286335, 2023). "who, in a murine model of ovarian cancer, showed that artesunate induced Th1 differentiation of CD4+ via miR-142-mediated downregulation of sirtuin 1, resulting in enhanced ovarian cancer apoptosis." (PMID 36700235, 2022). "In ovarian cancer, it has been reported that induction of PIAS4 by hypoxia prevents the binding of the transcriptional activator SP1 to the SIRT1 promoter, inducing EMT activation." (PMID 35887358, 2022). "The observed increase in SIRT1 expression was related to the nuclear form and was correlated with the expression of KRAS in endometriosis-related ovarian cancer." (PMID 33435147, 2021). "It has been reported that SIRT1 induces HMGB1 expression, thereby modulating ovarian cancer behaviors." (PMID 33343352, 2020). "SIRT1 is reportedly upregulated by HIF-1α and is involved in the promotion of cancer stem cell-like properties in ovarian cancer." (PMID 31068761, 2019). "In human ovarian cancer cells, HIF-1α promotes CSC-like properties by upregulating SIRT1 expression." (PMID 31428052, 2019). "SIRT1 is also known to have a significant role in induction of epithelial to mesenchymal transition (EMT) and therefore further contribute to ITH in ovarian cancer." (PMID 31366178, 2019). "B16F10 and human ovarian cancer (SKOV3 and SNU840) cells were more proliferative in co-culture with SIRT1-overexpressiong fibroblasts." (PMID 26992208, 2016). "We therefore compared the SIRT1 expression in human wild-type and doxorubicin resistant ovarian cancer cells and examined the effects of 15d-PGJ2 on this SIRT1 gene expression." (PMID 21957481, 2011). "Subsequently, the authors identified a new SIRT1 inhibitor, MHY2245, which induces autophagy and inhibits energy metabolism in human ovarian cancer cells through the PKM2/mTOR pathway, providing new insights into the treatment of ovarian cancer." (PMID 36975503, 2023). "SIRT1 expression was not upregulated but downregulated in PCa, bladder cancer (Nikas, Paschou & Ryu, 2020), and ovarian cancer cells." (PMID 37180577, 2023). "We tested the involvement of Sirt1 and RXRα in RSV-induced apoptosis in ovarian cancer cell lines." (PMID 34870752, 2022). "In the present study, we demonstrated that HOTAIR/miR-138-5p axis could regulate the DDP-resistance of ovarian cancer by potential targets EZH2 and SIRT1, which could shed light on new therapeutic targets for ovarian cancer treatment." (PMID 32349783, 2020). "With regard to cancer, Sirt1 was postulated as an anticancer target, e.g., promoting epithelial-to-mesenchymal transition (EMT) in many cancer types but it was also reported to suppress EMT in types like ovarian cancer." (PMID 32426286, 2020). "Another epigenetic factor, Sirtuin-1 (SIRT1), a histone and non-histone deacetylase, has been reported to be overexpressed more prominently in early stages of ovarian cancer, and is associated with poor prognosis." (PMID 31366178, 2019).
ovarian carcinoma (continued). "Conversely, under hypoxic conditions, SIRT1 is a direct downstream target of hypoxia-inducible factor 1α (HIF-1α), which orchestrates with NF-κB pathway to promote cancer stem cell-like properties in ovarian cancer cells." (PMID 31068761, 2019). "Finally, the NF-κB signaling pathway is involved in hypoxia-induced SIRT1 up-regulation, strengthening the link between this class III lysine deacetylase and ovarian cancer." (PMID 30319549, 2018). "Analysis of the frequently observed proteins by ANOVA confirmed increases in mean precursor intensity in ZFN91, TRPM5, SIRT1, CHD6, RIMS1, LOC101930455 (XP_005275896), CCDC37 and GIMAP4 between ovarian cancer versus normal female and other diseases or controls by the Tukey–Kramer HSD test." (PMID 30598658, 2018). "Moreover, SIRT1 was found to be the downstream target gene of HIF-1α, which was involved in the promotion of cancer stem cells-like features in ovarian cancer cells by hypoxia, and NF-κB signaling pathway was involved in hypoxia-induced SIRT1 up-regulation." (PMID 28878214, 2017). "Moreover, Sirtuin type 1 (SIRT1) was found to be the downstream target gene of HIF-1α, which was involved in the promotion of CSCs-like features in ovarian cancer cells induced by hypoxia." (PMID 28878214, 2017). "However, the expression of SIRT1 in carcinoma ovarian patients did not correlate with age, stage, location of metastasis, or capsular penetration." (PMID 33435147, 2021). "Given that artesunate positively or negatively regulated miRNAs expression, we proposed the hypothesis that artesunate may down-regulate Sirt1 through miR-142 to promote Th1 differentiation from CD4+ T cells, thus enhancing its anticancer effect against ovarian cancer." (PMID 31038546, 2019). "Nevertheless, these findings seem not to be transferable to all ovarian cancer cells, as RSV did not decrease Sirt1 expression in carboplatin-resistant cell lines." (PMID 34870752, 2022). "Unfortunately, the effect of RSV on Sirt1 and RXR expression in ovarian cancer cells has not been well documented until now." (PMID 34870752, 2022).
osteoporosis (86 papers, 2010 to 2026). A condition of reduced bone mass, with decreased cortical thickness and a decrease in the number and size of the trabeculae of cancellous bone (but normal chemical composition), resulting in increased fracture incidence. "The deletion of the oxygen-sensing enzyme proline hydroxylase 2 (PHD2) in osteocytes activates SIRT1, inhibiting Sost (encoding sclerostin) gene transcription via reduced H3K9ac enrichment in its promoter region and attenuating osteoporosis in HU mice." (PMID 40153585, 2025). "Preclinical studies showed that mice treated with SIRT1 agonists exhibited bone loss resistance in different osteoporosis models, suggesting SIRT1 as an attractive pharmacological target to counteract bone loss in aging." (PMID 39846667, 2025). "Among these investigations, there is a predominant emphasis on SIRT1 and its association with osteoporosis, followed by attention toward SIRT3 and SIRT6." (PMID 38264287, 2023). "Further experiments will be conducted to study the role of Sirt1 in other organs for improving dysfunction caused by VD deficiency, such as osteoporosis and muscle atrophy." (PMID 35906886, 2022). "Previous studies have shown that SIRT1 can reduce bone loss and promote bone formation in mice, indicating that it exerts a protective role in osteoporosis." (PMID 34711685, 2021). "SIRT1is a longevity associated protein; activation of SIRT1 in mice was associated with a delay in the onset of many aging-related diseases, including osteoporosis." (PMID 32532246, 2020). "Activation of SIRT1 in mice is associated with a delay in the onset of many aging-related diseases, including osteoporosis." (PMID 28937996, 2017). "As aging is associated with reduced Sirt1 level and activity, the influence of STACs on Sirt3 needs to be investigated in vivo in animal and human disease models of aging and osteoporosis." (PMID 26226624, 2015). "In this study, we performed deep mining of high-throughput RNA-sequencing (RNA-seq) data from 576 young and aged skeletal stem/progenitor cells (SSPCs) and identified SIRT1 downregulation as a critical hallmark of SSPC ferroptosis during aging-related osteoporosis." (PMID 42193234, 2026). "Ageing is a risk factor for osteoporosis, and SIRT1 expression declines with age." (PMID 37239124, 2023). "Recent animal studies indicate that longevity-associated Sirt1 may serve as an attractive pharmacological target for the treatment of osteoporosis and other bone related disorders." (PMID 33110391, 2020). "It implied that resveratrol may activate the expression of SIRT1 protein in osteoblasts of the osteoporosis rats to prevent bone loss via decreased bone transformation." (PMID 31804494, 2019). "It is noticeable that SIRT1 activators, such as resveratrol, stimulate bone formation and prevent the loss of bone mass, which may provide a new strategy for the therapy for osteoporosis." (PMID 31804494, 2019). "In human ageing, steroid hormone signalling can also be inferred from the link between declining oestradiol levels and reproductive senescence (menopause) typified by a predisposition to cardiovascular disease, cognitive impairment and osteoporosis all of which are also linked to SIRT1." (PMID 31746335, 2019). "Integrating innovative drug therapies with nonpharmacological interventions, such as regular physical exercise and caloric restriction, known to promote SIRT1 activation could contribute to mitigating the progression of osteoporosis and reduce the risk of fragility fractures." (PMID 40564069, 2025). "Whether these STACs or other STACs inhibit osteoclast-mediated bone resorption or influence other Sirtuins in vivo remains to be investigated in disease models of osteoporosis, aging and impaired metabolism as these conditions are associated with reduced Sirt1 level and function." (PMID 26226624, 2015). "The discovery of highly potent and safe SIRT1 activators therefore holds significant translational value for clinical anti-osteoporosis therapies." (PMID 42193234, 2026).